CADM1 (cell adhesion molecule 1)
Diseases named in the same sentence as CADM1 in open-access papers (continued):
Sharing a sentence is not in itself a finding about the gene and the disease.
tumor (continued). "A separate comparison of CADM1 gene expression in 3 normal keratinocyte (KJ, KV, KY) and 8 established SqCC cell lines (A431, SCC9, SCC12b, SCC13, SCC15, SCC27, SCC66, SCC71) revealed significant (>80%) or complete loss of CADM1 in 6 of 8 tumour cell lines compared with controls." (PMID 27035095, 2016). "However, we speculate that in human patients CRTAM-dependent immune surveillance of CADM1 expressing tumours may provide an additional mechanism by which CADM1 suppresses tumour growth." (PMID 27035095, 2016). "However, there are no reports on the incidence of cancer in these mice and thus whether Cadm1 is indeed a bona fide tumor suppressor gene." (PMID 22553910, 2012). "In addition, the tumor suppressive effect of Cadm1 in Mvt-1 cells was also lost." (PMID 23028344, 2012). "However, we cannot rule out the possibility that thymus-dependent, Cadm1-sensitive immune cells are indirectly associated with metastasis suppression by recruiting innate immune cells, including NK-cells, to eliminate tumor cells." (PMID 23028344, 2012). "We observed a marked increase in interferon-γ secretion in lymphocytes derived from the lymph nodes of Cadm1+ tumor bearing mice, indicating that an interferon-γ-mediated immune response local to the primary tumor may be involved in Cadm1-mediated metastasis suppression." (PMID 23028344, 2012). "DNMT1 produces hypermethylation of the genes’ promoter regions coding for the cell adhesion molecule 1 (CADM1) and suppressor of cytokine signaling (SOCS1), which are suppressors of malignant tumor development." (PMID 40510497, 2025). "The remaining three genes (e.g., CADM1, SPINK5 and TUSC3) were identified as tumor suppressor genes." (PMID 36675007, 2023). "Through regulation of different pathways (CADM1, SOCS2, Smad7, OTX1), miR-424-5p can act to inhibit tumor progression." (PMID 35409396, 2022). "Cancer cells in solid areas discard tumor-suppressive adhesion interactions such as CDH1, CADM1, and ESAM with normal epithelial cells in comparison with those in the GG areas." (PMID 35874770, 2022). "Several other putative tumor suppressors in the chromosome 1p or 11q deletion regions including CHD5, UBE4B, CADM1, and ATM, have patterns that are similar to KIF1B, where a subset of samples exhibit strong ASE in the absence of deletions." (PMID 35246212, 2022). "Further functional experiments are needed to elucidate the role of CADM1 on GIST biology, and there is a possibility that targeting therapy against CADM1 has a preventive effect for tumor spreading in small intestinal GISTs." (PMID 34257559, 2021). "CADM1 promoted the self-aggregation of ATLL cells, adhesion to endothelial cells, and increased tumor growth and invasion in xenograft mice." (PMID 34395444, 2021). "Previously, we reported that cell adhesion molecule 1 (CADM1), originally well known as a tumor suppressor in non-small cell lung cancer (NSCLC), is highly expressed in ATLL cells and promotes tumor growth and multiple organ invasion." (PMID 34407152, 2021). "Low expression of CADM1 protein and mRNA is evident in the tumor tissues of GBM patients, and the expression level of CADM1 is regulated by exosomal miR-148a." (PMID 34395444, 2021). "Upregulated LNMAT1 binds and recruits EZH2 to the cell adhesion molecule 1 (CADM1) promoter, silencing the expression of this tumor suppressor." (PMID 34638331, 2021). "(F) As in (E) where each cell is colored according to expression value of the genes CADM1 and CRTAM in tumor and non-tumor cells, respectively." (PMID 33155039, 2020). "(E) CADM1-CRTAM interaction: each cell is colored by patient (right, non-tumor and left, tumor cells)." (PMID 33155039, 2020). "In experiments using immunodeficient mice, highly CADM1-expressed ATLL cells activated tumor formation and aggressive infiltration of various organs, suggesting that CADM1 plays an important role in the tumor growth and invasion into organs of ATLL cells." (PMID 33419290, 2020).
tumor (continued). "Therefore, miR-194 might be useful to aid the suppression of CADM1 in the tumor cells." (PMID 33419290, 2020). "The insertion of CADM1 promotes ATLL cells to cause aggregation and adhesion to vascular endothelial cells, suggesting that CADM1 is a biomarker for acute ATLL and its involvement in tumor invasion." (PMID 33419290, 2020). "It has been found that CADM1 is a tumor suppressor factor and its expression is suppressed in GBM tumor cells." (PMID 32746854, 2020). "The cell adhesion molecule 1 (CADM1) is a molecule of cell adhesion with multiple functions and has been identified as a tumor suppressor gene." (PMID 33419290, 2020). "Particularly, TSLC1 (CADM1; cell adhesion molecule 1) located in 11q23.3 has an important role as tumor suppressor gene in NB and has also been related in oncogenesis." (PMID 31551474, 2019). "Cell Adhesion Molecule 1 (CADM1), CADM2, CADM3 and CADM4, serve as tumor suppressors and can inhibit cancer cell proliferation and induce apoptosis." (PMID 31480483, 2019). "CADM1 is ectopically expressed in ATL and promotes tumor growth and infiltration, whereas CADM4 is expressed in endothelial cells." (PMID 30131958, 2018). "We previously demonstrated that nectin-like molecule-2 (Necl-2)/cell adhesion molecule 1 cis-interacts with ErbB3 via the extracellular region and with the protein tyrosine phosphatase PTPN13, a tumour suppressor, via the cytoplasmic region." (PMID 28900130, 2017). "CADM1 (Cell Adhesion Molecule 1) is also highly expressed in ATLL cells, with a potential effect on cell-cell adhesion, tumor growth and organ infiltration." (PMID 29267225, 2017). "Cell adhesion molecule 1 (CADM1), an immunoglobulin superfamily (Igsf) adhesion molecule, is a well-known tumor suppressor for a variety of cancers of epithelial origin." (PMID 28335740, 2017). "EPB41L3 encodes band 4.1-like protein 3 (also known as protein 4.1B), which interacts with the synaptic cell adhesion molecule 1 (SynCAM1) to recruit NMDA receptors to synapses, and also acts as tumor suppressor." (PMID 25844147, 2015). "Finally, our results potentially implicate Cadm1 in cancer immunoediting, a process by which the adaptive immune system protects the host from developing cancer and, in turn, alters tumor progression by driving the outgrowth of tumor cells with decreased sensitivity to immune attack." (PMID 23028344, 2012). "Searches for putative TSGs have identified only few candidates, with tumor-specific promoter methylation, such as BLU and RASSF1A at 3p21, CADM1/TSLC1 at 11q23.1; THY1/CD90 at 11q22.3, CDH1 at 16q22.1, RASAL1, ADAMTS18 and CDH13 at 16q23." (PMID 18714356, 2008). "Interestingly, HeLa cells exposed to 20 μM capsaicin for a long time showed reversed hypermethylation of CADM1 and SOCS1, restoring the expression of these tumor suppressors." (PMID 40510497, 2025). "In nonsolid tumors, CADM1 contributes to the invasion of the tumor into vessels and other organs, suggesting that the prognostic significance of CADM1 is different in the types of tumors." (PMID 34064472, 2021). "In a pilot study of a cDNA expression chip using several GISTs, we found that Cell Adhesion Molecule 1 (CADM1), which could contribute to tumor growth and infiltration, is expressed more strongly in small intestinal GISTs than gastric GISTs." (PMID 34257559, 2021). "The positive CADM1 is mainly located in the marginal region of the tumor rather than in the center or randomly." (PMID 34064472, 2021). "In this sense, upregulation of tumor cell ligands MICA/B for activating NKG2D receptor, upregulation of adhesion CADM1 molecule, and downmodulation of E-cadherin ligand for inhibitory KLRG4 receptor, favor the elimination of tumor cell undergoing EMT by NK cells." (PMID 34858978, 2021). "In addition, the anti-CADM1 antibody inhibits the interaction of endothelial cells with CADM1+ ATLL cells, thereby suppressing tumor metastasis." (PMID 34395444, 2021).
tumor (continued). "CADM1 was first noticed as a suppressor gene of tumor in a non-small cell lung cancer, which was found as a favorable clinical factor in malignancies of solid tumors." (PMID 33419290, 2020). "In more detail, SIGLEC17P expression could be used by Tregs to circulate among all tissues; CD33, PCDH1, JAM2, CDHR3, and ITGA3 would orchestrate migration/retention in NI TDLNs; CADM1 in I TDLNS; and CEACAM6 in tumor." (PMID 32601304, 2020). "Moreover, we found that cell adhesion molecule 1 (CADM1), the established tumor suppressor in MM, was the downstream target of LNMAT1." (PMID 31334110, 2019). "Also, we identified NCAM1, CNTN1, SCG2, CADM1, IL-8, NPTX1, and APOD as PSCB in the tumor secretome." (PMID 31455042, 2019). "As before, we used a tumour xenograft model of luciferase transduced, CADM1 negative and CADM1 expressing A431 SqCC cells." (PMID 27035095, 2016). "Because SETDB2 knockdown led to significant inhibition of cell growth, migration and invasion, we further selected six tumor- or differentiation-related genes (WWOX, CADM1/TSLC1, CCDC80, NDRG1, CA9 and FZD9) that have been reported to show altered expression in several cancers including GCs." (PMID 27572307, 2016). "We also observed a complete lack of phospho-STAT3 staining in CADM1-expressing SqCC tumour xenografts (red)." (PMID 27035095, 2016). "Our results suggest that in HTLV-1 infected T-cell CADM1 does not have tumor-suppressor activity, but rather has gained tumor-promoting activity." (PMID 25774694, 2015). "Notably, the expression of either CADM1, 4.1B or MPP3 is lost in 11 of 12 lung tumor cell lines, suggesting that these proteins provide an important cascade for tumor suppressor." (PMID 25780926, 2015). "The CADM1 protein expression differed between primary tumor and BCBM with more negative staining among the BCBM samples (p = 0.011)." (PMID 24833255, 2014). "Normal breast duct showed an intensive membranous staining for CADM1, whereas the tumor stroma was CADM1 negative." (PMID 24833255, 2014). "70% (30/43) of the matched pairs showed a concordant CADM1 expression with 51% (22/43) of the primary tumor and lymph node samples being CADM1 negative and 19% (8/43) CADM1 positive in both types of tissues." (PMID 24833255, 2014). "Using logistic regression, thereby allowing for the controlling of confounders (alcohol use, tumor size, lymph node status, and smoking), patients positive for HPV16 had increased hypermethylated CADM1 (OR = 19.3, CI = 7.5–49.3) or TIMP3 (OR = 5.9, CI = 2.3–15.6)." (PMID 25065733, 2014). "Second, manipulation of Cadm1 in 6DT1 cells specifically affected the ability to form pulmonary metastases, without any significant effect on primary tumor growth." (PMID 23028344, 2012). "We demonstrate that Cadm1 can specifically suppress metastasis without affecting primary tumor growth." (PMID 23028344, 2012). "While we have not directly shown that Cadm1 expression resulted in tumor cell death by T cells, this notion is supported by previous studies showing Cadm1 expression on target cells enhances T cell cytotoxicity in an MHC-dependent manner." (PMID 23028344, 2012). "Unexpectedly, Cadm1-expressing Mvt-1 did not suppress tumor growth in this experiment as previously observed." (PMID 23028344, 2012). "Unexpectedly, Cadm1 did not alter tumor-cell-autonomous properties such as proliferation or invasion, but required the host's adaptive immune system to affect metastasis." (PMID 23028344, 2012). "We demonstrate that over-expression of Cadm1 by as little as 1.5-fold can specifically suppress metastasis without any resultant difference in primary tumor growth." (PMID 23028344, 2012). "In view of the limited success of classical genomic approaches towards the identification of NB tumour suppressor genes, we integrated high resolution array CGH with transcriptome analysis and identified CADM1 as a candidate 11q tumour suppressor gene with prognostic power." (PMID 18559103, 2008).
tumor (continued). "Although our study could not clarify the molecular-based mechanism of the CADM1-related development of cSCC, therapeutic applications for CADM1 might be desired for the detailed regulatory mechanisms of CADM1 in the tumor." (PMID 34064472, 2021). "Finally, they found that miR-148a containing exosomes could stimulate tumor development and metastasis by activation of STAT3 signaling via CADM1." (PMID 32746854, 2020). "Longitudinal tumour imaging revealed that ruxolitinib significantly and specifically reduced CADM1-null SqCC growth and metastases to a level that was indistinguishable from CADM1 expressing cells." (PMID 27035095, 2016). "Expression of Cadm1 in 6DT1 cells suppressed metastasis without significantly impacting primary tumor growth, suggesting that, Cadm1 might be functioning purely as a metastasis suppressor in this cell line." (PMID 23028344, 2012). "Whether miR-1246 and CADM1 expression are correlated in tumor tissues is not investigated before." (PMID 25159494, 2014). "Complementing EMT-promoting transcription factors, several metastasis suppressor genes (MSGs), such as CADM1, BRMS1, and KAI1/CD82, function to restrict metastatic dissemination without affecting primary tumor growth." (PMID 41409250, 2025). "The immunophenotype of typical ATLL tumor cells is positive for CD3, CD4, CD5, CD25, CCR4, and CADM1, and negative for CD7 and CD8." (PMID 35625999, 2022). "We also establish that treating CADM1 negative cancer cells with the clinically approved JAK/STAT inhibitor ruxolitinib can reduce in vitro and ex vivo tumour growth and metastases." (PMID 27035095, 2016).
cancer (100 papers, 2004 to 2026). A tumor composed of atypical neoplastic, often pleomorphic cells that invade other tissues. "Further exploration with Metascape highlighted associations of FABP4 and CADM1 with cancers (head and neck), while ENG was linked to congenital malformations of the circulatory system." (PMID 41398348, 2025). "In clear cell renal cell carcinoma as well, the expression of CADM1 is low, and it is involved in regulating cancer cell proliferation, invasion, and migration in association with CADM1-AS1." (PMID 34395444, 2021). "In particular, the loss of CADM1 expression is correlated with histological grades and cancer prognosis." (PMID 34395444, 2021). "CADM1 is essential for human health and is implicated in several diseases, such as cancer, autism spectrum disorder and venous thrombosis." (PMID 24465823, 2014). "It has been suggested that the disruption of cell adhesion through the loss of CADM1 is a mechanism leading to cancer cell invasion and metastasis." (PMID 24833255, 2014). "In mice, the CADM1 gene is implicated in cancer, radiation-induced lung fibrosis and bone structure." (PMID 24465823, 2014). "Variant 8/9 is susceptible to cleavage by proteases, such as a disintegrin and metalloprotease 10 (ADAM10), and γ-secretases, and it generates the membrane-bound fragment of CADM1 (MF-CADM1) on the cancer cell surface, whereas variant 8 was known to be a cleavage-resistant form of CADM1." (PMID 35805896, 2022). "On the contrary, data from at least two studies using various model systems have raised the possibility that EMT induction could increase cancer cell susceptibility to NK cells through up-regulation of NKG2D ligands or cell adhesion molecule 1 (CADM1)." (PMID 30301213, 2018). "Hence CADM1 is suggested to be a possible epigenetic diagnostic marker in predicting the risk of cancer progression." (PMID 27933097, 2016). "In cervical carcinogenesis, CADM1 silencing by promoter hypermethylation is a frequent event in the progression from high grade cervical dysplasia to cancer." (PMID 39869645, 2025). "In patients with adenocarcinoma, miR-423-5p inhibits CADM1 expression, aggravating the progression of the cancer." (PMID 40089674, 2025). "That CADM1 deregulation occurs in our models and in cancers strongly suggests that this is a virus-induced perturbation necessary for longer term and/or persistent infection." (PMID 39869645, 2025). "It has previously been shown that CADM1 expression is significantly reduced in HPV-driven cancers and this reduced expression correlates with hypermethylation of CpG islands at the CADM1 TSS." (PMID 39869645, 2025). "We therefore conclude that the rearrangement of CTCF binding and altered epigenetic regulation of the CADM1 locus is a pre-cursor to hypermethylation of the CADM1 promoter frequently observed in HPV-driven cancers." (PMID 39869645, 2025). "The best diagnostic performance for carcinoma was achieved with the combined methylation analysis of CADM1 and MAL (AUC = 0.912), which outperformed the individual markers: CADM1 (AUC = 0.770), MAL (AUC = 0.770), and PAX1 (AUC = 0.813)." (PMID 40564169, 2025). "Among the tested biomarkers, the combined methylation panel of CADM1/MAL exhibited the highest diagnostic performance for distinguishing histologic HSIL+ and carcinoma from low-grade lesions and NILM." (PMID 40564169, 2025). "ROC curve analyses further confirmed the superior performance of the combined CADM1/MAL methylation panel in detecting carcinoma (AUC = 0.912), compared to CADM1 and MAL alone (both AUC = 0.770) and PAX1 (AUC = 0.813)." (PMID 40564169, 2025). "For CADM1, methylation levels in the carcinoma group were significantly higher than those in NILM (p = 0.042), LSIL (p = 0.01), and HSIL (p < 0.001)." (PMID 40564169, 2025). "CADM1, a member of immunoglobulin superfamily and its characterization as a cell adhesion molecule, is also named as Necl-2 and SynCAM1 and plays significant roles in cancer, neurology and immunology." (PMID 37814227, 2023).